WNT2 (Wnt family member 2)
Diseases named in the same sentence as WNT2 in open-access papers (continued):
Sharing a sentence is not in itself a finding about the gene and the disease.
fragile X syndrome (1 paper, 2013). A genetic syndrome caused by mutations in the FMR1 gene which is responsible for the expression of the fragile X mental retardation 1 protein. "Wnt2 expression is reduced in the hippocampus and cortex of FMR1 knockout mice, a mouse model for Fragile-X syndrome." (PMID 23639831, 2013).
hypogonadotropism (1 paper, 2022). "The diminution of the key steroidogenic enzymes and the resultant decline in P4 and T levels suggests that HFD-HF diet-induced hypogonadotropism and a compromised Wnt2/GSK3β/β-catenin pathway disrupt the steroidogenic machinery in the ovary of adult rats." (PMID 36359843, 2022).
large cell lung carcinoma (1 paper, 2012). "The same regulatory effects of SOX2 on the expression of WNT1, WNT2, NOTCH1 and c-MYC were also observed in the human large cell lung carcinoma cell line H460 with SOX2 silencing.This finding indicates a universal regulatory mechanism of SOX2 on the oncogene network of both human lung cell lines." (PMID 22615765, 2012).
leiomyoma (1 paper, 2023). A well-circumscribed benign smooth muscle neoplasm characterized by the presence of spindle cells with cigar-shaped nuclei, interlacing fascicles, and a whorled pattern. "Many proteins such as F3, WNT2, CDH1, and LIF shown in the protein–protein interaction networks are well known in leiomyoma pathogenesis, and others, such as ICAM1, CXCL8, CCL2, and NANOG are novel and require further investigation." (PMID 36835153, 2023). "Here we showed that WNT2, WNT4, and WNT16 are overexpressed in leiomyomas, and that this upregulation was more pronounced in MED12-mutated leiomyomas compared to MED12 mutation-negative specimens, which is in line with previous reports." (PMID 36835153, 2023).
liver failure (1 paper, 2021). A liver disease characterized by the liver losing or has lost all of its function. "The WNT2 and HGF were also verified as targets of ID1 in resection‐induced liver failure in the mouse." (PMID 33635004, 2021).
metastasis (1 paper, 2019). The spread or migration of cancer cells from one part of the body (where they first appeared) to another. "Wnt2 expression in CAFs was significantly correlated with the depth of tumor invasion (P < .001), lymph node metastasis (P = .044), TNM stage (P = .010), venous invasion (P < .001), and recurrence (P = .013)." (PMID 31468733, 2019). "In conclusion, the present study showed that Wnt2 expression in CAFs was significantly related to factors leading to tumor progression, such as depth of tumor invasion and lymph node metastasis, as revealed by immunochemical examination." (PMID 31468733, 2019).
neuroendocrine tumor (1 paper, 2021). "We also studied if WNT2 expression was associated with expression of enteroendocrine cell/neuroendocrine tumor markers chromogranin A (CHGA) and synaptophysin (SYP)." (PMID 34274970, 2021).
ovarian adenocarcinoma (1 paper, 2021). An adenocarcinoma that arises from the ovary. "Moreover, PITX2 has been shown to interact with Wnt genes involved in canonical, noncanonical, or other pathways, such as WNT2/5A/9A/6/2B, to promote ovarian adenocarcinoma cell proliferation." (PMID 35071766, 2021).
prostate tumor (1 paper, 2008). "Several Wnt ligand including Wnt1 and Wnt2 are up-regulated in human prostate tumor samples." (PMID 18478098, 2008).
prostatic intraepithelial neoplasia (1 paper, 2015). "This was observed in a mouse model of prostatic intraepithelial neoplasia, where overexpression of Hmga2 in cancer-associated fibroblasts enhances expression of the Wnt ligands Wnt2, Wnt4, and Wnt9b, concomitant with enhanced Wnt signaling and nuclear β-catenin in adjacent neoplastic epithelium." (PMID 26244988, 2015).
Pulmonary hypoplasia (1 paper, 2014). "Using an ovine CDH model, in conjunction with pulmonary hypoplasia, we report a reduced expression of Wnt2, BMP4, and LGL1, key players in promoting proximal-distal patterning, branching morphogenesis, and regulating alveolization." (PMID 25593968, 2014).
respiratory failure (1 paper, 2014). The significant impairment of gas exchange within the lungs resulting in hypoxia, hypercarbia, or both, to the extent that organ tissue perfusion is severely compromised. "Wnt2 is expressed at high levels in fetal rat lung mesenchyme, and in Wnt2 deficient mice, 50% die shortly after birth, presumably due to respiratory failure." (PMID 25593968, 2014).
sarcoidosis (1 paper, 2018). Sarcoidosis is a multisystemic disorder of unknown cause characterized by the formation of immune granulomas in involved organs. "The observation of an uncommon recessive variant in the WNT2 gene (T1 patient) may be relevant of a pathogenic role of the canonical Wnt/ß-catenin signaling pathway in part of the inflammatory process occurring in sarcoidosis." (PMID 29510755, 2018).
skin cancer (1 paper, 2018). "For development of skin cancer it was reported that different Wnt isoforms are involved in epidermal carcinogenesis, in particular Wnt-7, as well as Wnt-2 and Wnt-5." (PMID 29416658, 2018).
thymoma (1 paper, 2022). A neoplasm arising from the epithelial cells of the thymus. "In addition to WNT4, the WNT2 gene was strongly expressed in B2 thymomas compared with B3 thymomas and TCs." (PMID 35965500, 2022).
thyroid cancer (1 paper, 2025). "Specifically, we overexpressed TNC in the TOPFLASH K1 thyroid cancer cell line and overexpressed Wnt-2 in a fibroblast cell line, WPMY." (PMID 39951495, 2025). "We show here that within thyroid cancer there is an interaction between TNC and Wnt-2 that leads to pathway activation." (PMID 39951495, 2025).
uveitis (1 paper, 2018). An inflammatory process affecting a part of or the entire uvea. "According to recent publications, our inferred genes (WNT2, WNT16, WNT3, WNT7A, and WNT7B) are functionally related to the initiation and progression of uveitis due to their interference to the proliferation of urea and mixed immune cells." (PMID 30349554, 2018). "Similarly, WNT2B (ENSP00000358698), WNT9A (ENSP00000272164), WNT4 (ENSP00000290167), and WNT2 (ENSP00000265441) all participate in the pathogenesis of uveitis through the regulation of urea cells, thus validating their strong relationships with uveitis." (PMID 30349554, 2018).
tumor (118 papers, 2007 to 2025). "In the tumor microenvironment, stromal cells, such as cancer-associated fibroblasts (CAFs), actively secrete Wnt2, which promotes the migration and invasion of CRC cells." (PMID 40943055, 2025). "Up‐regulation of lncRNA‐DAW expression was found in 50 paired (tumor/adjacent) HCC cases, which was also associated with elevated WNT2 expression levels in tumor samples." (PMID 40596757, 2025). "A study shows that targeting WNT2 secreted by tumor-associated fibroblasts can restore dendritic cell-mediated antitumor immunity, suggesting its important role in anti-tumor immunity." (PMID 39104385, 2024). "Previous studies have shown that Wnt/β-catenin signaling promoters such as Wnt1, Wnt2 and Wnt3a are associated with tumor proliferation and angiogenesis in NSCLC." (PMID 34465343, 2021). "In the present study, Wnt2 expression in CAFs was significantly associated with factors leading to cancer progression, such as depth of tumor invasion, lymph node metastasis, TNM stage, vascular invasion, and recurrence." (PMID 31468733, 2019). "High WNT2 expression was significantly associated with tumor size, lymphovascular space involvement, positive parametrium, and most importantly, PLNM." (PMID 27513465, 2016). "Associations of the expression of c-Fos, Wnt2, and Fzd9 with tumor clinical stages." (PMID 28665975, 2017). "Although combining anti-WNT2 with anti-PD-1 therapy shows promise, targeting cancer-associated fibroblasts (CAFs) may disrupt the tumor barrier, and the tissue-specific regulation of the WNT2 pathway increases the risk of adverse effects during clinical translation." (PMID 41050070, 2025). "WNT2 also drives tumor growth and invasion by activating Wnt/β-catenin signaling, particularly in OSCC cells." (PMID 40453074, 2025). "Although anti-WNT2 antibodies alone are less effective than standard chemotherapy like Alimta, their combination enhances tumor suppression." (PMID 40453074, 2025). "This core network of IL-19, TGFβ-1, CXCR4, BMP1, VCAN, and WNT2 reveals a tight-knit module that regulates tumor aggressiveness, immune evasion, and therapy resistance." (PMID 41348904, 2025). "Targeting WNT2 with monoclonal antibodies presents a potential strategy to disrupt tumor-stroma interactions, reducing tumor growth and metastasis." (PMID 40453074, 2025). "Among Wnt ligands, TNC exhibits the strongest correlation with Wnt-2, which is produced by CAFs at the invasive border with tumor cells, suggesting a possible interaction between Wnt-2 and TNC." (PMID 39951495, 2025). "Preclinical studies in breast cancer xenografts demonstrate that WNT2 silencing reduces tumor growth and overcomes chemotherapy." (PMID 40453074, 2025). "Compared to the corresponding normal tissues, the methylation level of WNT2/7B in tumor tissues was significantly reduced, leading to decreased transcriptional repression stability and subsequent overexpression." (PMID 41044153, 2025). "Key challenges include potential off-target effects on healthy tissues, efficient tumor delivery, and patient-specific variations in WNT2 expression and immune response." (PMID 40453074, 2025). "In malignant pleural mesothelioma (MPM), WNT2 expression correlates with poor prognosis and tumor progression." (PMID 40453074, 2025). "The TNC-expressing tumor cells along the leading edge are immediately adjacent to Wnt-2–producing fibroblasts." (PMID 39951495, 2025). "In colorectal cancer (CRC), WNT2 has also emerged as a pivotal factor in the tumor microenvironment." (PMID 40453074, 2025). "In CRC, reducing WNT2 expression in CAFs significantly reduced angiogenesis, whereas overexpressing WNT2 increased vessel density and tumor volume." (PMID 40038745, 2025). "These included WNT2, a key driver of the Wnt/β-catenin signaling pathway, which promotes tumor cell proliferation, invasion, and metastasis." (PMID 40722723, 2025).
tumor (continued). "WNT2 siRNA treatment produces similar effects by downregulating β-catenin and survivin, leading to tumor suppression in xenograft models." (PMID 40453074, 2025). "In oesophageal squamous cell carcinoma (OSCC), WNT2, a secreted glycoprotein that activates the Wnt/β-catenin signaling pathway and promotes tumor progression, has emerged as a significant factor in the TME." (PMID 40453074, 2025). "In comparison to non-tumor samples, it was observed that the protein levels of TGFβ-1, IL19, CXCR4, BMP1, VCAN, and WNT2 were significantly enhanced in several tumor samples." (PMID 41348904, 2025). "In vitro studies using CHO-Wnt2 conditioned media have shown that TF-secreted WNT2 promotes tumor cell growth and invasiveness." (PMID 40453074, 2025). "Tumor fibroblast (TF)-derived WNT2 stimulates cancer cell proliferation and invasion through this pathway." (PMID 40453074, 2025). "A combination of anti-WNT2 and anti-PD-1 monoclonal antibodies has been found to enhance anti-tumor T cell responses and improve the effectiveness of anti-PD-1 therapy in syngeneic mouse models of OSCC and CRC by increasing active DCs." (PMID 40453074, 2025). "We found that WNT2 is made by CAFs within the tumor microenvironment adjacent to the leading edge of tumor cells." (PMID 39951495, 2025). "WNT2 secreted by CAFs inhibits the anti-tumor T-cell response mediated by dendritic cells (DCs) through the SOCS3/p-JAK2/p-STAT3 signaling pathway." (PMID 39262952, 2024). "Targeting WNT2 secreted by CAFs restores DC differentiation and DC-mediated anti-tumor T cell responses in a CRC mouse model, enhancing the therapeutic effect of PD-1 antibodies." (PMID 39262952, 2024). "Wnt3 is directly present at the initiation phase, with Wnt2 appearing at the end to support the proliferation of cells in the tumour." (PMID 38397199, 2024). "These cells promote malignant tumor progression by secreting WNT2, and targeted inhibition of WNT2 restores DC differentiation and enhances the efficacy of ICIs." (PMID 38898505, 2024). "In a recent study, anti-Wnt2 mAb was found to significantly restore intratumoral anti-tumor T cell responses and enhance the efficacy of anti-PD-1 by increasing active DCS in both mouse OSCC and CRC syngeneic tumour models." (PMID 37374338, 2023). "In a xenotransplantation study, subcutaneous tumor growth rates in mice overexpressing WNT2 were increased and tumor vascular density significantly increased, thereby improving tumor angiogenesis." (PMID 35832030, 2023). "Anti-WNT2 mAb restored anti-tumour T-cell responses and increased active DC in mouse OSCC and CRC syngeneic cancer models." (PMID 37007004, 2023). "CAFs secret WNT2, which inhibits DC-mediated anti-tumor T-cell responses via the SOCS3/p-JAK2/p-STAT3 signaling cascade." (PMID 37124519, 2023). "In another study using colon CAFs, it was shown that canonical signaling via WNT2 enhances tumor progression by autocrine stimulation of fibroblasts and by inducing angiogenesis." (PMID 36683050, 2023). "WNT2 produced by CAFs suppressed anti-tumor T cell responses mediated by DC via SOCS3/p-JAK2/p-STAT." (PMID 37007004, 2023). "CAFs in colorectal, endometrial, and oesophageal cancers contribute to the secretion of Wnt5a, Wnt1, Wnt10b, and Wnt2, further promoting tumour proliferation, migration and relapse by activating canonical/noncanonical Wnt pathways." (PMID 38136392, 2023). "Some targets (PI16, WNT2) not only showed differential expression in T1CAFs, but also in CAFs from later tumor stages." (PMID 37085135, 2023). "In order to further prove that NE can regulate the expression level of WNT7A, we detected the expression levels of Wnt1, Wnt2, Wnt3a, Wnt4, Wnt5a, Wnt6, Wnt7a and Wnt10a in tumour tissues of anti-PD-1 mAb + Vehicle and NE + anti-PD-1 mAb + Vehicle groups." (PMID 36646807, 2023). "Anti-WNT2 monoclonal antibody significantly restores anti-tumor T-cell responses and enhances anti-PD-1 efficacy by increasing active DCs." (PMID 37124519, 2023).
tumor (continued). "In clear cell RCC, SNHG12, as a competitive endogenous RNA, competes with miR-30a-5p to bind to downstream oncogenes RUNX2, IGF-1R and WNT2 to promote tumor cell invasiveness." (PMID 35597996, 2022). "Wnt2 neutralizing antibodies seem to recall the immune response to the tumor through the activation of dendritic cells and FAP-targeted chimeric antigen receptor T cells, leading to depletion of FAP + CAFs, revoking the pro-angiogenic CAFs-related effect." (PMID 36139552, 2022). "The Wnt signaling pathway is a major mechanism in tumor biology, and the activation of this pathway involves various processes such as Wnt2, β-catenin, GSK3β, and Axin." (PMID 36861110, 2022). "Hh and Wnt pathways activation was assessed by immunohistochemistry (Gli1 and beta-catenin) on corresponding tumor tissues, and by plasma concentrations of Shh and Wnt (Wnt1, Wnt2 and Wnt3) at ICI introduction and at the first clinical evaluation." (PMID 33807552, 2021). "In vivo tumorigenesis experiments indicated HAGLR accelerated tumor growth via miR-335-3p/WNT2 axis." (PMID 34375306, 2021). "For example, WNT2 secreted by tumor fibroblasts promotes tumor cell proliferation and invasion via canonical signaling, and Wnt2-positive ESCC is correlated with lymph-node metastases." (PMID 34488905, 2021). "The combined in vitro and in vivo evidence showed that a WNT2/β-catenin/MMP signaling axis was required for tumor cell growth, migration, and invasion in ESCC." (PMID 32699215, 2020). "Our previous study showed that CAF-secreted WNT2 is a critical tumor microenvironment factor that can enhance ESCC cell motility and invasiveness." (PMID 32766155, 2020). "Taken together these results in addition to the mass spectrometry-based secretome analysis strongly underscore that WNT2 derived from colon CAFs supports tumor angiogenesis by increasing the secretion of pro-angiogenic factors in the microenvironment." (PMID 31667643, 2020). "In our RNAseq dataset, we identified only WNT2 in the WNT pathway as significantly highly expressed in the tumor samples compared to normal samples." (PMID 32699215, 2020). "Since co-injected human stromal cells rapidly disappear when co-injected with tumor cells, WNT2 was expressed directly in the tumor cells and tumor growth was evaluated." (PMID 31667643, 2020). "Further, injection of breast epithelial cells ectopically expressing Wnt2 into mice resulted in hyperplastic tumor development with significant fibrosis." (PMID 32983993, 2020). "In turn, in the CRC xenograft model, Wnt2 overexpression led to enhanced vessel density and tumor volume." (PMID 33276489, 2020). "We conclude that this in combination with the direct effect of WNT2 on EC migration and invasion contributes to elevated tumor angiogenesis in CRC." (PMID 31667643, 2020). "WNT pathway and WNT2 in particular appear to coordinate a peculiar invasive behavior that enhances tumor invasiveness, being, at the same time, a pivotal driver for immune escape in Npos PDAC." (PMID 31277479, 2019). "Wnt2 expression in CAFs was significantly correlated with depth of tumor (P < .001), lymph node metastasis (P = .044), TNM stage (P = .010), venous invasion (P < .001), and recurrence (P = .013)." (PMID 31468733, 2019). "We found strong correlations between Wnt2 expression and progression‐related variables such as tumor depth and lymph node metastasis." (PMID 31468733, 2019). "We used virally-encoded shRNAs targeting either WNT2 or WNT5A to deplete these genes in CAF cells and then mixed CAF cells with HCT116-eGFP cells to create WNT-negative tumor:CAF spheroids." (PMID 29245949, 2017). "In this report, we presented powerful evidences that high expression of c-Fos, Wnt2 and Fzd9 was found in human OS tissues and MG63 cells, and the level of c-Fos, Wnt2 and Fzd9 expression was correlated with tumor stages." (PMID 28665975, 2017).